NR2F1 (nuclear receptor subfamily 2 group F member 1)
Description:
Coup (chicken ovalbumin upstream promoter) transcription factor binds to the ovalbumin promoter and, in conjunction with another protein (S300-II) stimulates initiation of transcription. Binds to both direct repeats and palindromes of the 5'-AGGTCA-3' motif. Represses transcriptional activity of LHCG.
Synonyms: EAR-3; EAR3; ERBAL3; TFCOUP1; COUP-TFI; TCFCOUP1; SVP44; COUPTF1; BBOAS; BBSOAS
Tractability: Small molecule: it belongs to a druggable protein family. PROTAC: ubiquitination databases record sites on it; its protein half-life has been measured.
Target class: Nuclear hormone receptor subfamily 2; Nuclear hormone receptor subfamily 2 group F; Nuclear receptor; Transcription factor; Nuclear hormone receptor subfamily 2 group F member 1
Gene: Protein-coding gene on chromosome 5 (93,583,222 to 93,594,611, forward strand). Ensembl gene ENSG00000175745.
Subcellular location: Nucleus
Subcellular location (Human Protein Atlas): Nucleoplasm; Cytosol
Pathways (Reactome):
Gene expression (Transcription): Nuclear Receptor transcription pathway
Gene Ontology:
Molecular function: DNA-binding transcription factor activity; DNA-binding transcription repressor activity, RNA polymerase II-specific; protein binding; RNA polymerase II cis-regulatory region sequence-specific DNA binding; sequence-specific DNA binding; sequence-specific double-stranded DNA binding; nuclear receptor activity; retinoic acid-responsive element binding; zinc ion binding
Biological process: negative regulation of transcription by RNA polymerase II; cell differentiation; nervous system development; signal transduction; intracellular receptor signaling pathway; negative regulation of neuron projection development; positive regulation of transcription by RNA polymerase II; regulation of DNA-templated transcription
Cellular component: nucleus; nucleoplasm
Genetic constraint (gnomAD): Loss-of-function variants: 1 observed, 35.79 expected, observed/expected ratio (o/e) 0.0279, 90% interval 0.009 to 0.13. The upper end of that interval is the gene's LOEUF score, 0.13, which puts it in group 1 of 6, group 1 being the genes least tolerant of losing a copy. Missense variants: 267 observed, 575.17 expected, observed/expected ratio (o/e) 0.46, 90% interval 0.42 to 0.51. Synonymous variants: 275 observed, 266.56 expected, observed/expected ratio (o/e) 1.03, 90% interval 0.93 to 1.14.
Gene-disease validity (ClinGen):
ClinGen rates the evidence that NR2F1 causes each of these diseases.
Bosch-Boonstra-Schaaf optic atrophy syndrome (autosomal dominant): Definitive.
Homologues: Orthologues: chimpanzee NR2F1 (100% identical), macaque NR2F1 (100% identical), pig NR2F1 (99% identical), mouse Nr2f1 (99% identical), rat Nr2f1 (99% identical), tropical clawed frog nr2f1 (94% identical), zebrafish nr2f1a (94% identical), dog NR2F1 (92% identical), zebrafish nr2f1b (80% identical), guinea pig NR2F1 (53% identical), Caenorhabditis elegans nhr-32 (24% identical), Caenorhabditis elegans nhr-69 (23% identical), and 22 more. Paralogues in human: NR2F2 (86% identical), NR2F6 (60% identical), RXRA (41% identical), RXRG (39% identical), RXRB (38% identical), NR2C2 (38% identical), NR2E3 (37% identical), NR2C1 (34% identical), HNF4A (33% identical), NR2E1 (33% identical), HNF4G (32% identical).
Diseases named in the same sentence as NR2F1 in open-access papers:
NR2F1 is named in the same sentence as 100 diseases in open-access papers, as found by Europe PMC text mining. Sharing a sentence is not in itself a finding about the gene and the disease. The quoted sentences say what the papers report.
breast carcinoma (28 papers, 2011 to 2025). "The research of biomarkers associated with bone metastasis in breast cancer examines IL-1β expression, NR2F1, and others as possible indicators of bone metastasis or dormant disseminated tumor cell state." (PMID 41465319, 2025). "NR2F1 is also a strong candidate gene for breast cancer susceptibility, and greater transcript levels are related to resistance to the development of mammary carcinoma." (PMID 37306188, 2023). "The current study demonstrated that NR2F1 expression in the bulk tumor of primary breast cancer is associated with decreased cell proliferation and cancer stem cell-like characteristics." (PMID 35740627, 2022). "High NR2F1 expression in the bone marrow of DTC-positive breast cancer was associated with a better prognosis, indicating that NR2F1 induces durable growth arrest in metastatic cells." (PMID 35740627, 2022). "The tumor dormancy marker NR2F1 expression in primary breast cancer is associated with less cell proliferation, and it is predominantly expressed in cancer-associated fibroblasts in the tumor microenvironment." (PMID 35740627, 2022). "(ii) A mirror-image expression of the NR2F1 transcript with those encoding the Vav2, Vav3 and E-cadherin proteins in a large variety of human breast cancer cell lines." (PMID 30087437, 2019). "The in silico analysis of microarray datasets also suggested that the abundance of VAV2 and VAV3 transcripts is associated with low and high levels of CDH1 and NR2F1 transcripts in human breast cancer cell lines, respectively." (PMID 30087437, 2019). "We present NR2F1 as a strong candidate breast cancer susceptibility gene and MEC differentiation gene." (PMID 23785296, 2013). "In summary, these analyses indicate that low transcript levels of NR2F1 are strongly associated with high histological grade, poorly differentiated, highly proliferative breast cancers, including therapy-resistant ‘triple-negative’ breast cancer." (PMID 23785296, 2013). "Clinical evidence associates NR2F1 expression with early breast cancer recurrence." (PMID 39605887, 2024). "Other variants outside of the conserved element (perhaps located in closer genomic proximity to the NR2F1 promoter) may confer similar NR2F1 regulation and thus potentially associate with breast cancer risk." (PMID 23785296, 2013). "Considering Nr2f1 as the main target of the Mcs1a locus, we also looked at its transcript levels in mammary glands (MG), rat mammary epithelial cells (RMECs) and mammary carcinomas (carc.; induced by DMBA and MNU) from susceptible congenic control (WF.Cop) and Mcs1a resistant congenic rats." (PMID 23785296, 2013). "Therefore, we investigated the association of NR2F1 expression with breast cancer survival." (PMID 35740627, 2022). "Recently, soluble factors released by macrophages have been reported to induce NR2F1 and dormancy in disseminated breast cancer cells." (PMID 36757577, 2023). "Breast cancer dormancy gene signatures have recently identified NR2F1 as a gene with increased expression in dormant cells." (PMID 37306188, 2023). "NR2F1 has been proposed as a marker to identify dormant DTCs in the bone marrow of breast cancer patients, but it was recently shown to be expressed also in cancer-associated fibroblasts in primary tumors." (PMID 36757577, 2023). "We used two primary breast cancer single-cell sequencing cohorts, Cohort 1 and 2, where 5.1% and 2.7% of cancer cells excluding the other cell types expressed any NR2F1 mRNA (NR2F1-positive group), respectively." (PMID 35740627, 2022). "Given that breast cancer is a heterogenous disease, it was of interest to investigate the survival outcome by NR2F1 expression of each subtype." (PMID 35740627, 2022). "Previous studies mentioned that NR2F1 was highly expressed in DTCs We found that NR2F1 is most predominantly expressed in CAFs in the TME of primary breast cancer." (PMID 35740627, 2022).
breast carcinoma (continued). "The low expression level of POU5F1 and YY1 and high expression level of HEY1, IFNA13, NKX2-3, and NR2F1 were significantly related to poor prognosis in breast cancer." (PMID 34457116, 2021). "Out of those transcriptional factors we decided to focus on Nr2f1 (also known as COUP-TFI), an orphan nuclear receptor belonging to the steroid/thyroid hormone receptor superfamily previously involved in breast cancer cell dormancy." (PMID 30087437, 2019). "We also observed that the transient expression of Nr2f1 results in the reduction of CDH1 mRNA levels in three independent human breast cancer cell lines that display an epithelial phenotype (T47D, MCF7, BT474)." (PMID 30087437, 2019). "We analyzed the NR2F1 expression in DTCs by double immunofluorescence (DIF) staining of extra cytospins prepared from 114 BM samples from 86 selected DTC-positive breast cancer patients." (PMID 30322396, 2018). "To explore the functional state of the DTCs, we optimized double immunofluorescence (DIF) protocols for detection of NR2F1 and Ki67 on DTCs and analyzed selected BM samples from these three breast cancer cohorts with comparison to clinical parameters." (PMID 30322396, 2018). "Relative to the normal gland, mammary-tumors contain smaller and equal amounts of NR2F1 and NR2F2, respectively." (PMID 26894976, 2016). "We show the correlation of low NR2F1 transcript levels with high-grade and discuss the implication of this finding for human breast cancer." (PMID 23785296, 2013). "We queried 12 large publicly available human breast cancer gene expression studies and found that the median NR2F1 transcript level is consistently lower in ‘triple-negative’ (ER-PR-HER2-) breast cancers as compared with ‘receptor-positive’ breast cancers." (PMID 23785296, 2013). "Median NR2F1 transcript levels were found to be lower in triple-negative breast cancers, as compared with ‘receptor positive’ (non-triple-negative) breast cancers." (PMID 23785296, 2013). "Recently, NR2F1 was presented in a breast cancer dormancy gene signature as a gene upregulated in dormant cells." (PMID 23785296, 2013). "Nr2f1 transcript levels were found to be downregulated in whole mammary gland, RMEC and mammary carcinoma samples from susceptible congenic controls as compared with Mcs1a resistant congenic rats." (PMID 23785296, 2013). "In addition, we show that low NR2F1 transcript levels are associated with upregulation of cell cycle-related genes and high histological grade (grade 3, poorly differentiated, highly proliferative) in human breast cancers, including triple-negative therapy-resistant breast cancers." (PMID 23785296, 2013). "These analysis suggest that the human breast cancer and the MD mouse MG gene expression data sets are particularly similar in genes anti-correlated with NR2F1/Nr2f1, which are strongly enriched with genes involved in cell cycle/proliferation." (PMID 23785296, 2013). "Again, consistent with our findings, this result provides functional evidence that lower NR2F1 transcript levels increase the proliferative potential of breast cancer cells in an in vivo model system." (PMID 23785296, 2013). "To investigate its translational potential we analyzed NR2F1 transcript levels in available global gene expression data for human breast cancers." (PMID 23785296, 2013). "There is a moderate amount of evidence that NR2F1 is involved in breast cancer, mainly through its cross-talk activities with the ER-, the arylhydrocarbon receptor-, and/or retinoic acid-mediated signaling." (PMID 23785296, 2013). "Using this rat-mouse-human comparative genetics approach we identified Nr2f1 as a novel gene target for the development of breast cancer prevention or therapeutic strategies." (PMID 23785296, 2013). "Our findings highlight the orphan nuclear receptor NR2F1 as a novel target for breast cancer prevention and/or intervention strategies." (PMID 23785296, 2013).
breast carcinoma (continued). "In both the mouse mammary gland and a human breast cancer global gene expression data set, we found Nr2f1 transcript levels to be strongly anti-correlated to a gene cluster enriched in cell cycle-related genes." (PMID 23785296, 2013). "Notably, NR2F1 was markedly reduced in several cancers, such as head and neck squamous cell carcinoma and breast carcinoma." (PMID 39219375, 2024). "We hypothesize that high expression of the NR2F1 gene in the primary breast cancer tumor microenvironment (TME) maintains the quiescence of cancer cells and is associated with clinical outcomes in breast cancer patients." (PMID 35740627, 2022). "The Aguirre-Ghiso group recently demonstrated that NR2F1 agonist treatment induced cancer cell dormancy, which raised an expectation that NR2F1 expression in primary breast cancer may have the possibility to be a biomarker." (PMID 35740627, 2022). "NR2F1-high primary breast cancer amplified multiple pathways related to metastasis: Epithelial Mesenchymal Transition (EMT), angiogenesis, as well as enhanced cancer stem cell-related pathways, including KRAS signaling, Notch signaling, Hedgehog signaling, and Wnt/β-catenin signaling." (PMID 35740627, 2022). "Overall, we conclude that NR2F1 detection in BM DTCs may be a promising tool to determine the phenotype of DTCs and the prognosis of breast cancer patients." (PMID 30322396, 2018). "Raising NR2F1 transcript levels, or enhancing NR2F1's activities has great potential as a strategy to aid in breast cancer prevention or breast cancer intervention, including for triple-negative breast cancer (and possibly excluding HER2-positive breast cancer)." (PMID 23785296, 2013). "Since Nr2f1 is implicated in MEC proliferation and differentiation in mice and rats, we asked if NR2F1 transcript levels correlate with clinical features of human breast cancer." (PMID 23785296, 2013). "Our data suggest that the non-protein coding locus Mcs1a regulates Nr2f1, which is a candidate modifier of differentiation, proliferation, and mammary cancer risk." (PMID 23785296, 2013). "In addition, for thyroid cancer, breast cancer, and others, NR2F1 is considered an oncogenic gene." (PMID 38103068, 2023). "As nuclear receptor subfamily 2 group F member 1 (NR2F1) is a biomarker of dormancy shown in experimental settings, we studied its clinical relevance by analyzing comprehensive gene expression profiles of approximately 7000 breast cancer patients using computational biological approaches." (PMID 35740627, 2022). "Recent evidence demonstrated that inhibition of DEC2 and nuclear receptor subfamily 2 group F member 1(NR2F1) resulted in increased growth of breast cancer cells and downregulation of DEC2 interrupted tumor cell dormancy, indicating DEC2 might involve in tumor dormancy." (PMID 33990215, 2021). "The orphan nuclear receptor NR2F1, another mediator of p38 MAPK, can initiate dormancy in several cancer types, including breast cancer." (PMID 39605887, 2024). "Further, both NR2F1 and TGFB1 gene expressions were significantly higher in bone metastatic derivatives compared with wild-type 4T1 murine breast cancer cells." (PMID 35740627, 2022). "Interestingly, the dormancy regulator (Nr2f1) first identified in a murine prostate cancer model also serves as a biomarker for dormant DTCs in breast cancer patients, suggesting that while there are clear differences between the cancer types, there may be common dormancy-related genes." (PMID 35093137, 2022). "In breast cancer, eight winning TFs (ZBTB16, KLF2, KLF4, NR2F1, EGR1, FOSB, EPAS1, and GPRASP1) can form a coregulatory network, and three other winning TFs (MYBL2, FOXM1, and TAL1) can form another coregulatory network." (PMID 36101460, 2022). "In summary, BCPRS and BCPRS-related genes (HEY1, IFNA13, NKX2-3, NR2F1, POU5F1, and YY1) can be used to evaluate the immune microenvironment and tumor purity in breast cancer patients." (PMID 34457116, 2021).
breast carcinoma (continued). "Expression of the six BCPRS genes (IFNA13, HEY1, NKX2-3, NR2F1, POU5F1, and YY1) in breast cancer tissues was analyzed using Tabula Muris's FACS and droplet methods." (PMID 34457116, 2021). "A multivariate Cox regression model was employed to establish a predictive model containing 6 characteristic genes (HEY1, IFNA13, NKX2-3, NR2F1, POU5F1, and YY1) correlated with the prognosis of breast cancer." (PMID 34457116, 2021). "NR2F1 provokes a reduction in chemokine CXCL12 expression and enhancement of CXCR4 expression, and it stimulates breast cancer cell migration." (PMID 31146704, 2019). "Unlike mesenchymal markers such as αSMA, fibroblast-specific protein 1 (FSP1), and fibroblast activation protein (FAP), NR2F1 has not been described to be highly expressed in breast cancer CAFs." (PMID 35740627, 2022). "Conversely, there was no consistent association between NR2F1 expression and survival among the three cohorts, and no coherent relationship was observed between NR2F1 expression in primary breast cancer and distant metastases." (PMID 35740627, 2022). "Further, NR2F1 expression in breast cancer cells did not consistently correlate with stem cell-like traits." (PMID 35740627, 2022). "Furthermore, neural network-based deep learning models were established to predict breast cancer cell types using BCPRS-related genes (HEY1, IFNA13, NKX2-3, NR2F1, POU5F1, and YY1)." (PMID 34457116, 2021). "Therefore, a neural network-based model was constructed to predict cell types in breast cancer tissues based on genes YY1, POU5F1, NKX2-3, NR2F1, HEY1, and IFNA13." (PMID 34457116, 2021). "(B) Survival analyses (time to systemic relapse/breast cancer death) in relation to NR2F1 profile of DTCs for patients being nonmetastatic at time point of last DIF DTC-positive BMA and having no subsequent BM analyzed; NeoTax study patients excluded." (PMID 30322396, 2018). "Taken together the available results indicate that NR2F1 and NR2F2 are characterized by onco-suppressive properties in breast cancer, suggesting that strategies aimed at increasing their expression levels or aimed at stimulating their transcriptional activity are likely to be of therapeutic value." (PMID 26894976, 2016). "Finally, we asked if Nr2f1 transcript level anti-correlated with histological grade within both ER-positive/ER-negative and within both HER2-positive/HER2-negative breast cancer subtypes." (PMID 23785296, 2013). "In accordance with this finding, estrogen receptor (ER)-negative and progesterone receptor (PR)-negative breast cancers had lower median transcript levels of NR2F1 as compared with their positive counterparts." (PMID 23785296, 2013). "Additionally, in the GSE5460 data set the grade 3 HER2-positive breast cancers were found to have higher NR2F1 transcript levels as compared with the grade 3 HER2-negative breast cancers, suggesting a regulatory effect of HER2 amplification on NR2F1 transcript levels." (PMID 23785296, 2013). "Since COUP-TFs (including NR2F1) are nuclear hormone receptors, whose crystal structure suggests these are ligand controlled, identification of the ligand for NR2FI could provide a potential breast cancer therapeutic." (PMID 23785296, 2013). "Notably, NR2F1 transcript levels were found to be lower in human epidermal growth factor receptor 2 (HER2)-negative breast cancers (that mostly are ER-positive), as compared with the more aggressive HER2-positive breast cancers." (PMID 23785296, 2013). "The second row shows MNCs with a cluster of four breast cancer cell line cells (SKBR3), of which the lower left cell does not contain any NR2F1 signals and is therefore defined as NR2F1low." (PMID 30322396, 2018). "The human breast cancer cell line MCF7 and breast epithelial cell line MCF10A were transfected with siRNAs against NR2F1 (siNR2F1) and non-targeting control siRNA (siCONTROL)." (PMID 23785296, 2013).